IL6 (interleukin 6)
Diseases named in the same sentence as IL6 in open-access papers (continued):
Sharing a sentence is not in itself a finding about the gene and the disease.
infection (continued). "Temporal analysis of inflammatory cytokine induction revealed that while SARS-CoV-2 infection of parental THP1/PMA cells did not result in induction of pro-inflammatory responses, infection of CD169+ THP1/PMA cells led to rapid induction of IL-6, TNFα, IL-1β, and IFNλ1 mRNA expression." (PMID 36279285, 2022). "However, infection with G-614G demonstrated a significant reduction in IL-6 and IFN-β in the lower COPD airway with a trend toward inhibition of CXCL10 when compared to non-diseased individuals." (PMID 36496442, 2022). "Traditionally, IL-6 is a pro-inflammatory cytokine involved in stimulating an immune response during infection which may very well be the case with these findings." (PMID 35846741, 2022). "IL-1β, TNF-α, IFN-γ, and IL-6 plasma levels were measured on d2, d4, d6, and d8 post-infection." (PMID 36456548, 2022). "Interleukin 6 (IL-6) is a pleiotropic cytokine produced in response to infection and tissue damage." (PMID 36465934, 2022). "In addition, the expression of IL-6 after HAdV26 infection in A549 and SK-OV-3 cell lines was higher than that induced by HAdV5 infection." (PMID 35458402, 2022). "But, in RIP3-/- mice or in MLKL-/- mice, IL-17B had little infection to the plasma IL-6 and TNF-α." (PMID 36046722, 2022). "C. rodentium infection significantly increased the colonic expression of genes encoding for TNF-α and IL-6 at day four post infection compared to non-infected mice (p < 0.05)." (PMID 36266398, 2022). "And the benefits of IL-6 in detecting infection in NHL cases were also verified." (PMID 35463642, 2022). "Similarly, E. coli 1587 infection stimulated upregulation of IL-1β, IL-6, IL-10, and TNF-α mRNA transcription levels in mouse colons at 3 dpi, but this phenomenon mostly diminished in 7 dpi except for IL-6." (PMID 35643532, 2022). "IL-6 may provide a mechanistic link between infection and altered DNA methylation as it promotes nuclear translocation of DNMT1, the major enzyme responsible for maintaining methylation patterns following DNA replication." (PMID 36590303, 2022). "In this study, we investigated expression of pro-inflammatory cytokine genes in epithelial cells infected with HAdV26 and found that HAdV26 infection of human epithelial cells triggers the expression of pro-inflammatory cytokines, namely IL-6, IL-8, IL-1β, and TNF-α." (PMID 35458402, 2022). "Furthermore, these authors reported that siRNA knock-down of CARD19 in A549 and HEK293T cells resulted in reduced transcription of IFNβ and IL-6 upon stimulation with 3pRNA or infection with VSV." (PMID 35406738, 2022). "Furthermore, IL-6 in PD effluent correlates with subclinical infections (e.g., biofilms on PD catheter)." (PMID 35563220, 2022). "However, hemolymph did not influence the production ofIFN-γ, IL-12, IL-6, and IL-10 during infection." (PMID 35910486, 2022). "IL-6, on the other hand, is known as an acute-phase inflammatory marker that releases inflammatory cytokines from activated inflammatory cells and triggers proinflammatory signaling to prevent infection." (PMID 35884890, 2022). "In addition, IL-6, IL-8 is an important cytokine that activates chemotaxis in neutrophils and granulocytes, which then migrate toward the infection site." (PMID 35694270, 2022). "The levels of inflammatory factors in the colon tissues of CRKP colonization-challenged mice were significantly higher than those in normal mice, with significantly enhanced TNF-α, IL-1β, and IL-6 expression, and translocated infection further enhanced the expression of IL-6." (PMID 36445086, 2022). "For instance, increased periodontal pathogen abundance will enhance the stimulation of TLRs, induce Th1 to secrete IL-2, IFN-γ, TNF-α to kill intracellular infection pathogens, and then induce Th2 to secrete IL-4, IL-5, IL-6, IL-13 to regulate humoral immunity and limit Th1 response." (PMID 35254118, 2022).
infection (continued). "Therefore, monitoring the levels of IL‐6 along with other pro‐inflammatory markers provides evidence of how the patient's immune response is reacting during the infection." (PMID 36176597, 2022). "IFNγ, IP-10 and IL-2 responses were strongly elevated in individuals with prior C. burnetii antigen exposure, whether through infection or vaccination, while IL-1β, IL-6 and TNFα responses were slightly increased in naturally exposed individuals only." (PMID 35812430, 2022). "In our present study, we confirmed that TLR signaling-related genes, including Tlr4, Nfkb, Myd88, Cd14, Il6 and Tnf, are gradually increased in the AP mouse model following induction of the infection and become highly expressed when lesion formation accompanied by bone destruction is established." (PMID 33510341, 2021). "Moreover, another cytokine IL-6 is also linked with the severity and death during human VL, which is due to the inhibition of TNF-α in the early stage of infection and consequently by inhibiting the Th1 responses." (PMID 33680991, 2021). "To analyze whether the concentration of IL-6 is released or decreased upon infection with Ads, we analyzed IL-6 concentrations in supernatants of transduced samples." (PMID 34208817, 2021). "Interference with IL6 expression markedly enhanced the intracellular infection of E. tarda." (PMID 34439908, 2021). "Additionally, infection of BMDMs with the pknF deletion mutant resulted in increased pyroptosis, while the IL-6 production remained unchanged compared to Mtb-infected cells, suggesting that the mutant did not affect the priming step of inflammasome activation." (PMID 34324582, 2021). "Notably, LF pre-infection treatment (unwashed) resulted in decreased expression of IL1B and IL6 transcripts, proinflammatory cytokines associated to the cytokine storm." (PMID 33498631, 2021). "Treatment of trophoblast cells with cytokines, such as interleukin (IL)-1β and IL-6, elicited similar responses indicating that infection may alter placental nutrient uptake and fetal transfer." (PMID 34394055, 2021). "IL-6 was detected to host defense against infections and tissue injuries." (PMID 34970527, 2021). "There is a considerable association between the rise in IL-6 and PCT, which suggests that the rise in IL-6 may represent the patient’s infection to some extent." (PMID 34925324, 2021). "The treatment of infection was associated with a decrease in Treg level and a switch in their phenotype, namely, a decreased expression of ICOS and of naïve Treg and a systemic IL-6 and IL-4 inflammatory response." (PMID 34111180, 2021). "In addition, we found a sustained upregulation of multiple inflammatory transcripts in iron-loaded FthΔ/Δ mice as early as 12 hours after infection and the resultant massive overproduction of the key proinflammatory cytokines IL-1β, IL-6, and TNF-α." (PMID 34236052, 2021). "IL-6 promotes the terminal differentiation of B cells and T cell survival and helps T cells to overcome suppression by Tregs; its most noticeable role is in the defense against infection." (PMID 34093528, 2021). "In addition, the IL-6 mRNA expression level in group II was lower (p < 0.05) compared with group I at day 7 post-infection." (PMID 34988139, 2021). "IL-6 is involved in the regulation of the acute phase response to injury and infection." (PMID 35071302, 2021). "The mRNA of IL-4 on the 24th day after infection, IL-8 on the 24th and 40th days, and IL-12p40 on the 40th day were significantly up-regulated; IL-6 mRNA was up-regulated during the test period, while IL-10 mRNA was significantly down-regulated on the 3rd and 31st days after infection." (PMID 34988138, 2021). "ADAM-17 is considered to be the key molecule that may explain uncontrolled IL-6 trans-signaling and increased proinflammatory responses during infection." (PMID 33628091, 2021). "However, upon infection, challenge with microbial antigens or tissue damage, levels of IL-6 and IL-11, and OSM can increase tremendously." (PMID 34047814, 2021).
infection (continued). "The GO terms “regulation of NIK / NFκB signalling” and “interleukin-6 production” were determined for Erk1/2 inhibition only after infection with the capsule-deficient mutant, but not the wild-type strain." (PMID 34863201, 2021). "Cytokines and chemokines, including Interleukin 1 (IL-1), Interleukin 6 (IL-6) and Interleukin 8 (IL-8) are key modulators of the innate response—involved in recruiting immune cells to the site of infection and activating pathogen-killing mechanisms, often leading to inflammation." (PMID 34446770, 2021). "Macrophages are an important source of cytokines in response to inflammatory or infectious stimuli; indeed, T. cruzi-infected macrophages treated with rIL9 demonstrated reduced TGF-β and increased IL-6 levels after 72 h of infection compared with the corresponding levels in untreated infected cells." (PMID 34722343, 2021). "Both KO and WT cleared infection similarly but there were noted to be higher percentages of lymphocytes in SP-A KO mice and lower levels of IL-6 compared to WT, indicating that SP-A may modulate the immune response in this model." (PMID 35071140, 2021). "However, post infection, levels of IL-1β and IL-6 were significantly elevated in Coch+/+ mice compared to Coch−/− mice, suggesting that cochlin is necessary for local upregulation and increased secretion." (PMID 34768980, 2021). "There was a 500-fold increase in IL-6 mRNA by day 5 after infection." (PMID 33477869, 2021). "B. longum BB536 enhances the activities of neutrophils and NK cells, reduces fever in human beings, reduces IL6 and IFN-γ at the late stage of infection, and prevents body weight loss and virus replication in the lungs of mice infected with the influenza virus." (PMID 33897683, 2021). "Since serum CRP levels and some of the clinical signs of infections are depressed as the result of IL-6 inhibition, diagnosis of infections may be difficult." (PMID 34803441, 2021). "The B.1.351 infection resulted in a >25-fold increase in IL-6 and CCL2 mRNA expression." (PMID 35062231, 2021). "Interleukin 6 (IL-6) is also important in the progression of infection, inflammation and cancer." (PMID 33768009, 2021). "(B) The levels of IL-6 at 24 and 48 h were higher than that of Dlm before administration (P<0.05), but were similar to that of H37Rv group (P>0.05) and were lower than that of infection group (P<0.05)." (PMID 35003120, 2021). "From the two indigenous genotypes (D and G), infection with genotype D did not release any of the inflammatory cytokines as compared to that of the other genotypes whereas infection with genotype G showed significantly higher TNF-α IL-6, IL-8, IP-10 production in infected neuronal cells." (PMID 34493781, 2021). "Indeed, lethal infection with MRSA upregulated the production of IL-6, TNF-α, and MCP-1 in the circulation and organs such as the liver, lungs, and kidneys, which was correlated with the induction of CD38 associated with pro-inflammatory macrophages." (PMID 34681611, 2021). "IFN-γ, TNF-α, IL-1β, and IL-6 can promote inflammation when tissue injury or infection occurs." (PMID 33564301, 2021). "The relative expression levels of IL-6 in the hemolymph antibacterial protein treatment group were significantly different from those in the saline group on days 5 and 7 after thermal injury and infection." (PMID 34941846, 2021). "Levels of SAA1, IL-6, and IP-10 were found to increase after infection." (PMID 34943175, 2021). "The influenza virus A/FM/1/47 (H1N1) infection could substantially upregulate the serum levels of IL-1β and IL-6." (PMID 34497658, 2021). "IL-6 is the main force that triggers the proinflammatory response during infection." (PMID 33628091, 2021). "Maternal stunting and infection at delivery were associated with a non-significant trend of increased risk of elevation of newborn IL-6." (PMID 34836049, 2021).
infection (continued). "We also measured Tnfa, Il1b, Il6 and Isg15 expression and found that macrophages infected with plasmid-cured R. equi (33701-) had reduced expression of Tnfa at 8h, and of Il6 at both 4- and 8h after infection." (PMID 34473814, 2021). "In PBMCs, monocytes and T-cells are the likely sources of IL-6 during an infection." (PMID 33668216, 2021). "The TNF-α and IL-6 levels gradually decreased with time post-infection." (PMID 33717010, 2021). "Similarly, human infection show strong cytokine production, including IL-6, IL-8, IL-12, TNF-α, CSF2, IFN-γ, IL-10, CCL2, CCL3, CCL4, and CCL714–16." (PMID 34615921, 2021). "This dampened induction of IFN-β and downstream ISGs likely permits rapid viral replication in vivo, leading to elevated viral loads observed on day 8 post-infection, which was accompanied by elevated concentrations of the pro-inflammatory cytokines, IL-6 and IP-10." (PMID 33653328, 2021). "Moreover, the percentage and number of DCs in TLR7 KO mice at 6 weeks post infection significantly decreased compared to WT mice, and the percentage of IL-6-secreting DCs also decreased." (PMID 34692568, 2021). "Il-6 can regulate the growth and differentiation of various cells, regulate immune response, acute phase response, and hematopoietic function, and plays an essential role in the anti-infection immune response of the body." (PMID 34925532, 2021). "For example, elevated infection-evoked production of multiple cytokines and chemokines, including IL-6 has been detected after infection with flaviviruses in serum and cerebrospinal fluid of patients, brain tissue samples from mice and primary human cortical astrocyte cultures." (PMID 33897376, 2021). "Both young and old RMs showed increased infiltration of inflammatory immune cells (CD8+, CD163+, and CD11b+ cells) after infection, whereas inflammatory factor-secreting cells (IFN-α+, IL-6+, and IL-1β+ cells) were only significantly induced in old RMs following infection." (PMID 34471088, 2021). "There was a non-significant trend of increased risk of IL-8 and IL-6 elevation with history of ante-and intrapartum infections, respectively." (PMID 34836049, 2021). "However, the prognostic values of IL-6 are controversial due to the short window in which IL-6 rises and falls during inflammation and infection." (PMID 34120605, 2021). "TIGF infection with F. nucleatum induced IL-6 and IL-8 secretion in TIGFs, albeit to a lesser extent than in primary cells, indicating that TIGFs are capable of responding to infection through TLR4, but this response is diminished compared to primary cells in the absence of TLR2." (PMID 34031466, 2021). "Of note, ongoing infection‐related inflammation could be the reason for high D22 IL‐6 levels in the intermediate group." (PMID 33369136, 2021). "In addition, observed multisystem inflammatory syndrome in children and adolescents (MIS-C) infection with elevated levels of immunoglobulins, C-reactive protein, ferritin and interleukin-6 indicate possible 4-week post-viral immunisation in the body." (PMID 34685427, 2021). "Estrogen deficiency following menopause causes an age-related increase in IL-6, even in the absence of infection, trauma or stress." (PMID 33535169, 2021). "The rapid secretion and metabolism of IL-6 are intensively correlated with acute neutrophilia in the infected area, which suggests a distinct role for activated neutrophils in controlling cytokine induction in S. suis-induced infection." (PMID 33318141, 2021). "However, despite the weak replication level at high MOI, we were able to detect some cytokine response following infection as observed by the expression of IL-6, IFN-β and CCL5 in brain endothelial cells." (PMID 34386007, 2021). "Therefore, an increase in IL-6 level that was observed in this study is meant for the protection of the host cells against infection and tissue damage." (PMID 33767260, 2021).
infection (continued). "Infection and inflammation induce hepcidin, predominantly through the effects of the cytokine interleukin-6 (IL-6), and increased concentrations of hepcidin then inhibit ferroportin activity, leading to depletion of iron in plasma and extracellular fluid (hypoferremia)." (PMID 34204327, 2021). "Clinical indications in severe malaria were found to be linked with the blood stage of infection with an excessive release of inflammatory cytokines (TNF-α, IL-6, and INF-γ) which contribute to further severity of infection such as organ damage and severe anemia." (PMID 34975479, 2021). "IL-6-deficient mice did not develop severe lung pathologies until late in the course of infection, at a time when wild type mice are typically recovering, suggesting that the absence of IL-6 compromises recovery of the lung after infection." (PMID 33680987, 2021). "The analysis of variance between IL-1β, IL-18, IL-6, IL-8 and caspase-1 levels, showed statistically significant differences related to the infection conditions or the time after infection (6, 18 and 24 h.p.i.)as well as the interaction between these two factors." (PMID 34947890, 2021). "Interestingly, pre-FM treatment concentrations of haptoglobin, IL-6, and NEFAs were significantly different between infection outcome groups." (PMID 34073753, 2021). "After a severe infection, the pathway of T-helper (Th) 1-lymphocytes is hyperactivated, causing excessive production of CD14++ and CD16+ inflammatory monocytes responsible for exacerbating inflammation and increasing the plasma concentration of IL-6." (PMID 33946649, 2021). "IL-6 shares functional features with IL-21, and it is produced in certain tissues (bone, lung, liver, adipose tissue, muscle) to fulfill homeostatic functions as well as in response to infection, cancer and tissue injury." (PMID 34234771, 2021). "IL-6, a pleiotropic cytokine produced by a variety of cells, including macrophages, is considered to play a pro-inflammatory function in TB and to be important for control of MTb infection." (PMID 33671144, 2021). "The IL-6 level slightly increased from 8 h to 48 h post-infection." (PMID 34368012, 2021). "This suggests widespread immune dysfunction in IL-6 KO mice during infection." (PMID 34696354, 2021). "Based on our observations, it is our conviction that IL-6 shall be monitored throughout the infection and not only at admission and that anti-IL-6 therapy should be performed in patients with high IL-6 levels but before the expected peak, to try to avoid clinical deterioration." (PMID 33679753, 2021). "However, at sites of infection, the neutrophil lifespan increases due to the high levels of inflammatory cytokines, such as IL-1, TNFα, IL-6 and G-CSF, present in the local tissue environment." (PMID 33571211, 2021). "In such inflammatory responses, macrophages are known to play a role in host defense during the early stage of an infection by producing inflammatory mediators, such as nitric oxide (NO), interleukin-1β (IL-1β), interleukin-6 (IL-6), and tumor necrosis factor-α (TNF-α)." (PMID 34679773, 2021). "Cytokines were also involved in the immune responses to IAVs infections, and substantial increases in IL-6 cytokine levels were observed on 2 days after infection and gradually decreased over the course of infection, IFN-γ and IL-10 levels increased on 6 or 7 days after infection." (PMID 34060982, 2021). "Moreover, in this in vivo model of infection, daily treatment (orally administered) with 25 mg/kg/day Bzl induced a significant decrease in IL-1β, IL-6 and NOS2 in the heart and CK activity in serum, to normal levels." (PMID 34925364, 2021). "In this way, this study evaluated the impact of Il6 deficiency on mice testicles in the absence of infection or inflammation." (PMID 34075113, 2021).